MTOR (mechanistic target of rapamycin kinase)
Diseases named in the same sentence as MTOR in open-access papers (continued):
Sharing a sentence is not in itself a finding about the gene and the disease.
depression (continued). "Overall, mTOR signaling mediates the behavioral response of many antidepressant drugs, which also indicates a critical role of the mTOR signaling in depression." (PMID 36045116, 2022). "Our previous investigation based on network pharmacology revealed that SGKL targets the PI3K/Akt/mTOR pathway, indicating that SGKL might contribute to alleviating depression symptoms through the PI3K/Akt/mTOR pathway." (PMID 35713215, 2022). "Such a violation of synaptic connectivity can potentially result in the decrease in neurotrophic factors such as BDNF, the overall decrease in NMDA signaling, and the inhibition of mTOR signaling that subsequently leads to the manifestation of depression-like behavior." (PMID 34064233, 2021). "mTOR plays a role in memory and neuronal elasticity, and it is reasonable that mTOR activity is related to the pathophysiology of several CNS conditions, such as Huntington’s disorder, bipolar disorder and depression." (PMID 34832986, 2021). "Reduced mTOR signaling is reported in major depressive disorder, compared with healthy controls." (PMID 34122166, 2021). "Additionally, exifone-induced alterations in mTOR/Akt/PI3k signaling and eEF2 activity further supported HDAC1 in the synaptogenesis associated with neuroinflammation-induced depression." (PMID 33526073, 2021). "Thus, mTOR signaling has become integral for the preclinical evaluation of novel compounds to treat depression." (PMID 34445375, 2021). "GSK3B may be involved in the development of depression by inhibiting Erk-CREB-BDNF signaling, and PI3K/Akt/mTOR/GSK3B signaling may be the mechanism underlying the rapid antidepressant effects." (PMID 34976096, 2021). "Additionally, some KEGG pathways indicated by our analyses were associated with second-messengers and signal transduction, such as MAPK, PI3K-Akt or mTOR signalling pathways, which have been shown as dysfunctional in depression and under stress." (PMID 33322800, 2020). "The role of mTOR in depression and antidepressant responses." (PMID 32849818, 2020). "Accumulating evidences suggested that mTOR signaling was dysregulated in depression." (PMID 33192625, 2020). "Although our bioinformatics analysis identified the mTOR and PI3K/Akt signaling pathways, and both have been linked with depression, the literature still lacks information considering the regulation of miR-17-5p in both pathways (mTOR, p < 0.001; PI3K/Akt, p = 0.013)." (PMID 31125682, 2019). "Interestingly, other studies reported that some antidepressant drugs ameliorated depression via targeting the mTOR pathway." (PMID 31711501, 2019). "Ketamine has been shown to exert antidepressant-like effects in different animal models of depression by activation of the mammalian target of rapamycin (mTOR), by increasing the expression of synaptic proteins and increasing synaptogenesis in the prefrontal cortex." (PMID 30813226, 2019). "How the mTOR signaling pathway is relating to depression is discussed in many studies." (PMID 30618863, 2018). "On the other hand, α7-nAChR inhibition may exert antidepressant effects via activation of the mTOR pathway and upregulation of synaptic proteins, ameliorating stress/depression-induced atrophy in the hippocampus and PFC." (PMID 29961917, 2018). "The present findings may provide new insights into the mPFC dopaminergic system and mTOR signaling in the pathophysiology of depression and shed light on the development strategies of new antidepressants." (PMID 28630404, 2017). "Current studies implied that the impaired synaptic and structural plasticity may be mediated by the inhibition of mTOR signaling in depression." (PMID 28630404, 2017). "One explanation is that both NMDAR inhibition and stimulation converge on the activation of BDNF/mTOR signaling, indicating both receptor antagonists and agonists may be enlisted in treating depression." (PMID 28536503, 2017).
depression (continued). "In addition, it has been reported that PI3K/Akt/mTOR signaling pathway has differential role in mental illnesses including depression." (PMID 28790888, 2017). "Our present results indicated that the deficit of mTOR signaling in the mPFC may be due to a decrease of D1R/PKA signaling in the mPFC in depression." (PMID 28630404, 2017). "Signalling pathways, such as mTOR signalling and their effect on downstream synaptogenesis, synaptic plasticity, neurotransmission, and functional connectivity are keystones in the genesis of depressive disorders." (PMID 28491480, 2017). "Zinc administered in combination with AR-A014418, GSK-3β inhibitor, produced synergistic effects in the FST, suggesting that the antidepressant-like effect of zinc depends on GSK-3, which further supports the link between zinc and mTOR with regard to depressive disorders." (PMID 28299207, 2017). "The proteinogenic branched-chain amino acids (BCAAs) valine, leucine and isoleucine might play an unrecognised crucial role in the development of depression through their activation of the mammalian target of rapamycin (mTor) pathway." (PMID 27490818, 2016). "Recent studies support the hypothesis that major depressive disorder might a consequence of a disruption in mTOR-dependent translation regulation." (PMID 26522512, 2015). "In addition, we demonstrated that a single injection of sarcosine exhibited antidepressant-like effects in an FST depression model and rapidly activated the mTOR signaling pathway." (PMID 26150775, 2015). "Moreover, blockade of mTOR signalling by the specific antagonist rapamycin completely blocks the ketamine induction of synaptogenesis and behavioural responses in models of depression." (PMID 23862076, 2013). "More understanding of the precise intracellular mechanisms downstream of PI3K/AKT/GSK3/mTOR changes in mental illnesses could provide novel insights into the development of new therapeutic approaches having greater efficacy against major depression." (PMID 23320155, 2012). "Interestingly, a recent study has shown that the blockade of mTOR signaling completely blocked ketamine induction of synaptogenesis and behavioral responses in animal models of depression." (PMID 21647420, 2011). "Hence, IL-1β signaling may be a possible bridge mechanism between Akt/mTOR/NF-κB-mediated microglial hyperactivation and neurogenesis impairment in DG seen in mice model of depression." (PMID 40011631, 2025). "Moreover, due to the uncertainty regarding downstream proteins of AKT/mTOR signaling pathway that play an antidepressant role in depression, further research is necessary to reveal the more precise antidepressant mechanism of NAc-DBS for its expanded clinical use." (PMID 41234534, 2025). "However, the complete cellular signaling mechanism by which exercise alleviates HFD-induced depression-like behavior has not been elucidated, especially the molecular mechanism underlying the upstream mechanism of motor regulation of mTOR." (PMID 39389946, 2024). "In addition, FoxO signaling pathway and mTOR signaling pathway were also found, which may help to further understand the pathological mechanism of depression." (PMID 36325528, 2022). "Hence, a comparative assessment of morphological changes in the spino-dendritic system, as well as the expression level of mTOR in the BRS of patients with depression, could shed more light on the pathomechanism of this illness." (PMID 35269761, 2022). "Since hyperphosphorylation of both ERK and mTOR has been correlated to pro-apoptotic processes, mitochondrial damage, depression, and early life stress, we can hypothesize that the induction of the anorexic phenotype might drive similar effects, which need further detailed investigation." (PMID 36570702, 2022).
depression (continued). "The acute mTOR downregulation in the IL cortex leads to reduced BDNF mRNA levels in mPFC, together with impaired 5-HT and glutamate neurotransmission in the DRN, disturbances linked to neuropathophysiology of depression, as reported in preclinical and clinical studies." (PMID 34445375, 2021). "In addition, it was suggested that leucine could activate mTOR signaling pathway, which has a protective role in synaptic plasticity in stress and depression." (PMID 34413798, 2021). "Moreover, if BCAA imbalances and subsequent mTOR disturbances in the brain prove to be contributing factors to depression in COPD, newer antidepressants targeting mTOR may prove more effective in the COPD population." (PMID 34743729, 2021). "Moreover, though the anti-depressive effect of ketamine has been suggested to be mediated by activation of mTOR based on pre-clinical studies, a recent randomized control trial found that mTOR inhibition increased the effect of antidepressants in patients with major depression." (PMID 33132941, 2020). "Thus, the sequential activation of RagA, mTOR, and p70S6K could be a potential mechanistic link between bacterial infection and depression." (PMID 31711501, 2019). "Yet, deletion of GluN2B from pyramidal cells in the cortex and hippocampus may mimic and occlude ketamine actions on depression-like behavior, excitatory synaptic transmission, mTOR activation, and synaptic protein synthesis in response to six-fold higher drug doses (50 mg/kg) than used here." (PMID 30696941, 2019). "mTOR served as a negative regulator in autophagy, and the inhibitor of mTOR, known as rapamycin, exerted anti-depressive-like effects in rodents after sub-chronic treatment, which suggests that enhanced autophagy might contribute to the therapy of depression." (PMID 31480539, 2019). "Reduced activation of the mammalian target of rapamycin (mTor) due to a reduction of BCAAs might play a crucial unrecognised factor in the etiology of depression and may evoke depressive symptomatology and lower energy metabolism in patients with major depression." (PMID 27490818, 2016). "Taken together, a rapid and lasting remedy of mTOR-related signaling and glutamatergic function in the PFC may, at least in part, be mechanistically linked with rapid and lasting antidepressant actions in depression-like subjects." (PMID 26315757, 2015). "Mammalian target of rapamycin (mTOR), Ca2+/calmodulin-dependent protein kinase 2γ (Camk2γ) and glycogen synthase kinase-3β (GSK-3β) are three fundamental biomarkers implicated in the underlying mechanisms of depression, schizophrenia, mania and certain neuropsychiatric diseases." (PMID 24396420, 2014). "Thus, hippocampal mTOR signaling is likely involved in both the synaptoplastic and behavioral responses to PPN, although more specific tests of the behavioral endophenotypes of depression and anxiety are needed to strengthen this association." (PMID 24313960, 2013). "Administration of Schisandrae chinensis fructus showed a promising therapeutic effect on depression induced by CUMS though activation of BDNF and upregulation of TrkB/CREB/ERK and PI3K/AKT/GSK3β/mTOR signaling pathways." (PMID 40612748, 2025). "Meanwhile, the PI3K/Akt/mTOR signaling pathway, downstream of the BDNF/TrkB, is considered vital in the treatment of depression." (PMID 39796425, 2025). "Further, mTOR and PI3K inhibition also reduced the antidepressant-like effects of KNT-127 in an animal model of depression as assessed by SIT and SPT." (PMID 39643691, 2025). "In depression, rapamycin pretreatment before ketamine failed to blunt the acute antidepressant response and may have prolonged benefit, indicating pathway modulation without establishing mTOR hyperactivity as a primary causal driver." (PMID 41462744, 2025). "Previous experimental studies have shown that the mTOR inhibitor, and EVR analogue rapamycin can induce neuropsychological changes, such as anxiety and depression, in healthy rodents." (PMID 41141866, 2025).
depression (continued). "FMOD exhibits potential as a therapeutic target for depression related to TBI, with its protective effects potentially mediated through the PI3K/AKT/mTOR signaling pathway." (PMID 38864941, 2024). "Based on AKT, MAPK and mTOR signaling pathways, 11 key proteins (AKT/p-AKT, ERK12/p-ERK12, GluA-1, mTOR/p-mTOR, MEK1/p-MEK1, MEK2/p-MEK2, P38/p-P38, P70S6K/ p-P70S6K, PSD95, Syn1 and TrkB) were chosen to be validated by western blot in four depression models." (PMID 37308476, 2023). "In animal models of depression, a decrease in autophagy regulators such as Ulk1, AMPK, LC3II/LC3I and an increase in p62 and phosphorylated mTOR suggest reduced autophagy activation." (PMID 37122628, 2023). "We found that CUMS induced depression-like symptoms and reduced PI3K/Akt/mTOR phosphorylation in the hippocampus, which were ameliorated by long-term treatment." (PMID 36737776, 2023). "Roflumilast activates the AMPK/mTOR/ULK1 autophagy pathway and provides neuroprotective effects in the treatment of depression." (PMID 38026940, 2023). "In the hippocampus of the animal model of depression, LG upregulated the concentrations of 5-hydroxytryptamine (serotonin; 5-HT) and norepinephrine (NE) and acted on the PI3K/Akt/mTOR-mediated BDNF/TrkB pathway in the hippocampus." (PMID 35323721, 2022). "It has neuroprotective effects and prevent the occurrence of depression by upregulating the expression of TrkB, BDNF, and mTOR, as well as by downregulating the activity of the HPA axis." (PMID 36506414, 2022). "We next sought to determine which formulation was superior in treating mild-to-moderate COVID-19 with symptoms of depression or inflammation via targeting specific targets (GRM1, GRM5, mTOR and PLA2G4A)." (PMID 36210820, 2022). "The target-pathway network illustrated that AKT1, MAPK1, GSK3B, TNF, MTOR, and PTEN were core targets enriched in key signaling pathways that played crucial roles in the treatment of depression by CCHP." (PMID 34976096, 2021). "The importance of mTOR in the IL cortex in the neurobiology of depression could be complemented with the fact that the infusion of drugs as ketamine and (2R,6R)-hydroxynorketamine in this area in the rodent brain induce an antidepressant-like effect mediated by mTOR pathway activation." (PMID 34445375, 2021). "We found that CUMS induced depression-like symptoms and reduced PI3K/Akt/mTOR phosphorylation in the hippocampus were ameliorated by long-term SY treatment." (PMID 33584387, 2021). "Previous postmortem studies in patients with depression have uncovered deficits in the N-methyl-d-aspartate receptor (NMDAR) and mTOR signaling in the prefrontal cortex." (PMID 32424120, 2020). "Resolvins activated mTOR and MAP/ERK signaling in models of depression, while resolvins and maresins activated the NF-κB pathway in models of neurodegeneration and neurological disorders." (PMID 32180741, 2020). "RvD1, RvD2, and RvE1 exerted their effects through mTOR and MAP/ERK signaling in models of depression, while RvD1, RvD2, and MaR1 through the NF-κB pathway in models of neurodegeneration and neurological disorders." (PMID 32180741, 2020). "More importantly, AKT/mTOR signaling pathway, as a negative regulatory of autophagy, is involved in antidepressants counteract CORT-induced depression-like behavior." (PMID 31500666, 2019). "As reported for other rodent depression models, we observed that SPS decreased the phosphorylation levels of upstream proteins such as pAkt and pERK as well as mTOR and its downstream p4E-BP-1 and p70S6K in the hippocampus." (PMID 30089868, 2018). "These protein targets, especially hubs, and the functional nodes, MTOR, CDK6, SHC1, RCOR1 CCNA2 and STAT3, have been already reported to be involved in depression." (PMID 28954415, 2017). "There have been multiple studies concerning the role of VEGF in depression, with a focus on the PI3K/AKT/mTOR signal pathway influencing the process of pathogenesis and neurogenesis." (PMID 27057362, 2016).
depression (continued). "For the first time, we showed that a single dose of ketamine or Yueju reversed the effects of CMS on the activation of mTOR effectors 4E-BP1 and p70S6K in the PFC of depression-like rodents." (PMID 26315757, 2015). "The question raised is why the manipulation of the glutamatergic system by both NMDAR enhancers and blockades improves the symptoms of depression and shares final common targets AMPAR and mTOR for antidepressant effects." (PMID 26150775, 2015). "To investigate whether NAc-DBS relieves the hippocampal injuries and mitigates depression-like behavior in mice by enhancing the BDNF protein and activating the mTOR pathway, we used Western blots and RT-qPCR to detect changes in mTOR pathway." (PMID 41234534, 2025). "Thus, we can speculate that sustained mTOR activity, especially increased synaptic levels of downstream effectors (p-mTOR and total p70S6K) in the hippocampus, plays an important role in the resilience of GluN2A−/− mice to depression, which also confirms mTOR-mediated synaptic function." (PMID 39185814, 2024). "In summary, we hypothesize that exercise training may mediate the mTOR pathway and thus affect hippocampal synaptic plasticity, thereby alleviating HFD-induced depression-like behavior." (PMID 39389946, 2024). "In previous studies, we demonstrated that SHD can alleviate depression-like behavior and intestinal mucosal injury by modulating the gut microbiota, but few studies elaborated light on its therapeutic mechanism on tryptophan metabolism and AMPK/mTOR pathway." (PMID 39351096, 2024). "In the current work, the mechanisms underlying the antidepressant effect of RGZ, such as regulation of AMPK and mTOR, and their downstream signaling pathways of pAKT, p38MAPK, 4EBP1, and NGF, were investigated in a mouse model of depression induced by dexamethasone (DEXA)." (PMID 36979839, 2023). "Ketamine’s antianhedonic effect is an active area of investigation considering that preclinical studies suggest a synergistic effect of ketamine and lithium, highlighting activation of the mTOR pathway and GSK-3 inhibition, thus improving both depression–anhedonia and suicidality." (PMID 38137120, 2023). "Our results showed the phosphorylation of mTOR or p70S6K in mTOR signaling pathways were not altered in hippocampus of four depression models." (PMID 37308476, 2023). "Moreover, the pathophysiology of depression has been related to AKT, another upstream target of mTOR." (PMID 36979839, 2023). "Therefore, interaction between of miRs and gene encoded proteins has led to the identification of signaling pathways like neurotrophic signaling, mTOR signaling, and PI3k/AKT involved in depression." (PMID 36362315, 2022). "On the other hand, chronic stress disrupts mTOR signaling and markedly decreases synaptic proteins such as post-synaptic density 95 (PSD-95) and pre-synaptic protein synapsin I, indicating its role in the pathophysiology of depression." (PMID 36506414, 2022). "CUMS exposure also significantly decreased GSH, BDNF, phosphorylation of AKT, and mTOR in PFC, and antioxidant drugs such as resveratrol, 5-HT, or carvedilol can increase BDNF, AKT, and mTOR and decrease oxidative stress, significantly alleviating depression." (PMID 35663199, 2022). "On the basis of previous experiments and existing literature, we established a CUMS rat model to investigate whether MMXY can improve anxiety and depression-like behavior and protect rat retina by regulating the PI3K/Akt/mTOR signaling pathway." (PMID 36278192, 2022). "Altogether, these data indicate that there is no clear correlation between activity of mTOR pathway and side effects such as cognitive deficits, anxiety or depression." (PMID 33723223, 2021). "NH125 treatment reduced the phosphorylation levels of eEF2 and mTOR, while enhanced BDNF and eventually SNAP25 and PSD95 expression, suggesting an etiological role of eEF2 in LPS-induced synaptogenetic dysfunction and depression." (PMID 33526073, 2021).